IRX4 (iroquois homeobox 4)
Description:
Likely to be an important mediator of ventricular differentiation during cardiac development.
Synonyms: IRXA3
Tractability: PROTAC: ubiquitination databases record sites on it.
Gene: Protein-coding gene on chromosome 5 (1,877,413 to 1,887,381, reverse strand). Ensembl gene ENSG00000113430.
Subcellular location: Nucleus
Subcellular location (Human Protein Atlas): Nucleoplasm; Vesicles
Gene Ontology:
Molecular function: protein binding; DNA-binding transcription factor activity, RNA polymerase II-specific; RNA polymerase II cis-regulatory region sequence-specific DNA binding; DNA binding
Biological process: cell development; heart development; neuron differentiation; regulation of transcription by RNA polymerase II; establishment of animal organ orientation; negative regulation of transcription by RNA polymerase II; regulation of DNA-templated transcription
Cellular component: chromatin; nucleus
Genetic constraint (gnomAD): Loss-of-function variants: 20 observed, 25.73 expected, observed/expected ratio (o/e) 0.78, 90% interval 0.55 to 1.13. The synonymous counts are far from expectation, so gnomAD's model fits this gene poorly and the ratio says little. Missense variants: 827 observed, 631.07 expected, observed/expected ratio (o/e) 1.31, 90% interval 1.24 to 1.39. Synonymous variants: 376 observed, 297 expected, observed/expected ratio (o/e) 1.27, 90% interval 1.16 to 1.38.
Gene-disease validity (ClinGen):
ClinGen rates the evidence that IRX4 causes each of these diseases.
congenital heart disease (autosomal dominant): Limited. A heart disease that is present at birth.
Homologues: Orthologues: chimpanzee IRX4 (99% identical), macaque IRX4 (95% identical), dog IRX4 (89% identical), pig IRX4 (87% identical), mouse Irx4 (82% identical), rat Irx4 (80% identical), guinea pig IRX4 (67% identical), tropical clawed frog irx4 (61% identical), zebrafish irx4a (55% identical). Paralogues in human: IRX6 (35% identical), IRX3 (31% identical), IRX1 (30% identical), IRX5 (28% identical), IRX2 (28% identical), MKX (16% identical).
Diseases named in the same sentence as IRX4 in open-access papers:
IRX4 is named in the same sentence as 28 diseases in open-access papers, as found by Europe PMC text mining. Sharing a sentence is not in itself a finding about the gene and the disease. The quoted sentences say what the papers report.
prostate carcinoma (8 papers, 2015 to 2024). A carcinoma that arises from epithelial cells of the prostate gland. "The 5p15.33 prostate cancer risk locus is a small (∼6 kb) region harboring six prostate cancer associated SNPs in linkage equilibrium with each other, 7 kb upstream of the Iroquois Homeobox 4 (IRX4) promoter." (PMID 37971305, 2024). "Here, the authors functionally characterize a complex genetic variant relevant in prostate cancer that regulates IRX4 expression through epigenetic activation." (PMID 37612286, 2023). "Multiple reports have shown that the 5p15.33 prostate cancer risk region is a particularly strong expression quantitative trait locus (eQTL) for Iroquois Homeobox 4 (IRX4) transcripts." (PMID 37612286, 2023). "Genome-wide association studies have linked Iroquois-Homeobox 4 (IRX4) as a robust expression quantitative-trait locus associated with prostate cancer (PCa) risk." (PMID 38076926, 2023). "Iroquois-class homeodomain protein 4 (IRX4) is a TALE homeobox transcription factor which has been implicated in prostate cancer (PCa) as a tumor suppressor through genome-wide association studies (GWAS) and functional follow-up studies." (PMID 33919200, 2021). "The genome-wide significant association signal for ulceration was located on SSC16, nearby the IRX4 gene (Iroquois homeobox gene), that was identified by a GWAS for prostate cancer risk in humans." (PMID 29963229, 2018). "In addition to the GWAS SNPs, a multiple nucleotide length polymorphism (MNLP) near the IRX4 promoter has also been implicated in prostate cancer susceptibility." (PMID 37971305, 2024). "One such locus is the 5p15.33 cytogenetic region, where the regions associated with prostate cancer risk localizes to a small (~6 kb) region of linkage disequilibrium containing six strongly correlated candidate causal variants 7 kb upstream of the IRX4 promoter." (PMID 37612286, 2023). "Search by genomic interval applied to the genomic interval that includes the SNPs and the IRX4 promoter, identifies TF ChIP-seq peaks in prostate cancer cell lines, which are then be displayed on the data browser." (PMID 37971305, 2024). "Additionally, Iroquois-class homeodomain protein (IRX4) isoforms was identified to induce distinct functional programming, thereby contributing to suppressing the progression of prostate cancer." (PMID 38659038, 2024).
pancreatic cancer (5 papers, 2015 to 2025). "In pancreatic cancer, decreased expression of IRX4 was observed in 12 cell lines through hypermethylation of its promoter." (PMID 36980893, 2023). "The IRX4 promoter region was found to be frequently hypermethylated in pancreatic cancer, which provides an advantage for cell growth in pancreatic cancer." (PMID 33919200, 2021). "Moreover, the re-expression of IRX4 in pancreatic cancer cell lines was able to inhibit colony formation and cell proliferation." (PMID 36980893, 2023).
breast carcinoma (3 papers, 2011 to 2021). "High levels of IRX4 in breast cancer plasma samples have been reported, which suggest the potential of IRX4 as a biomarker for breast cancer." (PMID 33919200, 2021). "IRX4 expression was found to be downregulated in the mesenchymal cell population compared to epithelial cells in breast cancer." (PMID 33919200, 2021). "Enhanced expression of IRX4 has been detected in some human cell lines, such as brain cancer (BEWO), skin immortalized (HaCaT), lung immortalized (HBEC3-KT) and breast cancer (MCF7) cell lines (the Human Protein Atlas database)." (PMID 33919200, 2021).
cardiomyopathy (3 papers, 2017 to 2023). A disease of the heart muscle or myocardium proper. "Specifically, loss of IRX4, a member highly expressed in cardiomyocytes, causes cardiomyopathy characterized by cardiac hypertrophy and impaired contractile function." (PMID 37587150, 2023). "Irx4 knock out mice demonstrated cardiomyopathy with compensated increased Irx2 expression." (PMID 28430825, 2017).
cervical carcinoma (2 papers, 2021). A carcinoma arising from either the exocervical squamous epithelium or the endocervical glandular epithelium. "In addition, promoter DNA methylation levels (average beta values) of ALDH1A2, GATA4, GRIA4, and IRX4 were significantly elevated in primary cervical carcinoma as compared to normal tissues." (PMID 34745985, 2021).
colon cancer (2 papers, 2015 to 2023). "Specifically, a study discovered that patients with colon cancer had a worse prognosis when their blood levels of BTNL9 were greater, and IRX4 may play important roles in the development and progression of gastric cancer." (PMID 37359510, 2023).
ventricular septal defect (2 papers, 2020 to 2023). The presence of a defect (opening) in the septum that separates the two ventricles of the heart. "The role of the iroquois homeobox 4A (IRX4) gene has been reported in regulating chamber-specific expression of myosin isoforms and ventricular differentiation in animal models, and potential causal effects of its mutation in a ventricular septal defect in humans have been proposed." (PMID 32903789, 2020).
cervical squamous cell carcinoma (1 paper, 2021). A squamous cell carcinoma arising from the cervical epithelium. "13.8% of 297 cervical squamous cell carcinoma cases revealed that genetic alterations in the five-gene signature with a low frequency of ALDH1A2 (1.3%), OSR2 (1%), GRIA4 (4%), GATA4 (1%), and IRX4 (7%)." (PMID 34745985, 2021).
Hodgkins lymphoma (1 paper, 2021). A heterogeneous group of malignant lymphoid neoplasms of B-cell origin characterized histologically by the presence of Hodgkin and Reed-Sternberg (HRS) cells in the vast majority of cases. "Subsequent expression analysis of TALE homeobox genes in public datasets of Hodgkin lymphoma (HL) patients revealed overexpression of IRX3, IRX4, MEIS1, MEIS3, PBX1, PBX4 and TGIF1." (PMID 33539429, 2021).
melanoma (1 paper, 2018). A malignant, usually aggressive tumor composed of atypical, neoplastic melanocytes. "Interestingly, the TERT gene is located only 600 kb away from IRX4 and is now considered as a major player of melanoma predisposition." (PMID 29963229, 2018).
non-small cell lung carcinoma (1 paper, 2024). A group of at least three distinct histological types of lung cancer, including non-small cell squamous cell carcinoma, adenocarcinoma, and large cell carcinoma. "Previous research has confirmed that the knockdown of IRX4 can suppress stem-like characteristics and resistance to gefitinib in non-small cell lung cancer cells, although the specific mechanisms of IRX4 in PCa remain unclear." (PMID 39759507, 2024).
osteoporosis (1 paper, 2025). A condition of reduced bone mass, with decreased cortical thickness and a decrease in the number and size of the trabeculae of cancellous bone (but normal chemical composition), resulting in increased fracture incidence. "Additionally, irx4 is closely associated with bone density and osteoporosis." (PMID 39857294, 2025).
prostate tumors (1 paper, 2023). "Here, we unveil enrichment of androgen-responsive gene signatures in metastatic prostate tumors exhibiting heightened IRX4 expression." (PMID 38076926, 2023).
tumor (10 papers, 2015 to 2026). "IRX4 has been considered a putative tumor suppressor based on the observation that the SNP risk locus is associated with lower IRX4 expression." (PMID 37612286, 2023). "Collectively, these results indicate that the knockdown of IRX4 can inhibit the activity, migration, and proliferation of tumor cells, thereby impeding tumor growth." (PMID 39759507, 2024). "The opposite effect was observed when overexpression of IRX4 was induced, indicating tumor suppressor activity of IRX4 in PC." (PMID 36980893, 2023). "Concerning average beta values of GATA4, GRIA4, and IRX4, the patients with tumor stage IV had the highest level as compared to the subgroup patients with stage I/II/III tumor." (PMID 34745985, 2021). "IRX4 knockdown in a PC-9/GR xenograft tumor model inhibited tumor progression and the expression of NANOG and CD133 more effectively than single treatment alone." (PMID 32820157, 2020). "IRX4 has been described as a tumor suppressor in PCa with the interaction of vitamin D receptor." (PMID 33919200, 2021). "Therefore, understanding the AS of IRX4 in PCa could provide insights into tumor development and lead to the development of new therapeutic targets." (PMID 33919200, 2021). "A pan-cancer analysis with 10,967 tumor samples in 32 TCGA cohorts revealed that a low frequency of ALDH1A2 (1.4%), OSR2 (5%), GRIA4 (3%), GATA4 (4%), and IRX4 (5%) was genetically altered." (PMID 34745985, 2021). "Further, combined use of gefitinib and IRX4 knockdown significantly downregulated NANOG protein level in vitro, and markedly decreased tumor growth and the expression of NANOG and CD133 in vivo, than treatment with gefitinib alone." (PMID 32820157, 2020). "Even though IRX4 has been identified for its transcriptional role in the human heart and tumor suppressor role in PCa, the IRX4 proteins are so far not fully structurally and functionally characterized for their interactions and the functional domains." (PMID 33919200, 2021).
cancer (9 papers, 2011 to 2026). A tumor composed of atypical neoplastic, often pleomorphic cells that invade other tissues. "Besides PCa, the diversity of the IRX4 gene can be a hallmark for other cancers; thus, the characterization of these isoforms would augment our knowledge for the development of specific therapeutic strategies." (PMID 33919200, 2021). "Iroquois homeobox protein 4 (IRX4), a transcription factor expressed in multiple tissues, has been demonstrated to be implicated in the progression of many cancers." (PMID 41646966, 2026). "In summary, our research focused on the diversity of epithelial cells in high-grade PCa at the individual cell level, further revealing the significance of IRX4 in this cancer type." (PMID 39759507, 2024). "The effects of IRX4 downregulation increasing gefitinib cytotoxicity and inhibiting cancer stem-like properties are well demonstrated in a PC-9/GR xenograft mouse model." (PMID 32820157, 2020). "In light of our new data, we conclude that 1,25(OH)2D3 signaling-induced decreases in IRX4 inhibits NANOG-mediated cancer stem-like properties and gefitinib resistance in PC-9/GR cells." (PMID 32820157, 2020). "Based on the observations that inhibition of IRX4 decreased NANOG-mediated cancer cell stemness, we examined the relationship between 1,25(OH)2D3/VDR and IRX4-induced NANOG expression." (PMID 32820157, 2020). "Notably, several cancer-associated genes are located within a 1 Mb proximity including CLPTM1L, TERT, BRD9, TRIP13, NKD2, LPCAT1, and IRX4." (PMID 40278994, 2025). "Next, we analyzed cancer phenotypes as a function of IRX4 level." (PMID 37612286, 2023). "Proliferation only measures a single cancer-related phenotype so, if IRX4 is involved in tumorigenesis, it could be acting through mechanisms other than proliferation." (PMID 37612286, 2023). "Knockdown of NANOG inhibited the expression of CD133 and restored gefitinib cytotoxicity, and NANOG overexpression-induced cancer stem-like properties and gefitinib resistance could be obviously reversed by knocking-down IRX4." (PMID 32820157, 2020). "Of note, NANOG overexpression-induced cancer stem-like properties and gefitinib resistance could be obviously reversed by knocking-down IRX4." (PMID 32820157, 2020). "Whether TGF-β1 increased cancer cell stemness by regulating IRX4 and how to regulate TGF-β1 signaling mediated cancer stem-like properties is unclear." (PMID 32820157, 2020). "How to regulate IRX4-mediated cancer stem-like properties and gefitinib resistance?" (PMID 32820157, 2020). "The association between 1,25(OH)2D3 and TGF-β/Smad signaling pathway led us to consider whether TGF-β/Smad signaling pathway induces the IRX4-induced cancer stem cell-like properties." (PMID 32820157, 2020). "However, whether IRX4 regulate the cancer stem-like properties of EGFR-TKI resistant cells needs further study." (PMID 32820157, 2020). "Therefore, we speculate that TGF-β1 may increase EGFR-TKI resistance by regulating IRX4-induced cancer stem-like properties." (PMID 32820157, 2020). "In this study, the role of IRX4 in regulating EGFR-TKI resistance and cancer stem-like properties, and the effects of 1,25(OH)2D3 on regulating IRX4-mediated cancer cell stemness and EGFR-TKI resistance, were investigated." (PMID 32820157, 2020). "In summary, the roles of IRX4 downregulation increasing gefitinib cytotoxicity and inhibiting NANOG-mediated cancer stem-like properties were elucidated for the first time, to the best of our knowledge." (PMID 32820157, 2020). "In this study, we discovered that TGF-β1/Smad3 signaling increased IRX4 expression and NANOG-mediated cancer cell stemness." (PMID 32820157, 2020). "This complex isoform diversity of IRX4 gene may not be constrained to PCa but can deviate to other cancers with significant expression of IRX4; thus, it is worth exploring the pathological and/or physiological impact of them." (PMID 33919200, 2021).
infection (1 paper, 2020). The state of being infected such as from the introduction of a foreign agent such as serum, vaccine, antigenic substance or organism. "Both the group of shNC and shIRX4 had the similar infection efficiency, and the IRX4 expression was effectively knocked-down." (PMID 32820157, 2020).
prostate (1 paper, 2023). "While we clarified the functionally causal cis-regulatory mechanism of IRX4 expression, the biological relevance of this gene in driving prostate carcinogenesis remains incomplete." (PMID 37612286, 2023).
IRX4 also shares sentences with these, for which no sentence is quoted: congenital heart disease (2 papers); gastric cancer (2); Wilms tumor (2); brain cancer (1); cardiac hypertrophy (1); cardiac insufficiency (1); hypertensive disorder (1); ischemia (1); ischemic stroke (1); Kyphoscoliosis (1); liver cancer (1).